SLF1 (SMC5/6 complex localization factor 1)
Description:
Plays a role in the DNA damage response (DDR) pathway by regulating postreplication repair of UV-damaged DNA and genomic stability maintenance. The SLF1-SLF2 complex acts to link RAD18 with the SMC5-SMC6 complex at replication-coupled interstrand cross-links (ICL) and DNA double-strand breaks (DSBs) sites on chromatin during DNA repair in response to stalled replication forks. Promotes the recruitment of SLF2 and the SMC5-SMC6 complex to DNA lesions.
Synonyms: ANKRD32; BRCTD1; DKFZp761C121; DKFZp564C0469; BRCTx; hNSE5
Tractability: PROTAC: UniProt records ubiquitination sites on it; ubiquitination databases record sites on it.
Gene: Protein-coding gene on chromosome 5 (94,618,054 to 94,739,436, forward strand). Ensembl gene ENSG00000133302.
Subcellular location: Nucleus; Cytoplasm; Cytoplasm, cytoskeleton, microtubule organizing center, centrosome
Subcellular location (Human Protein Atlas): Nucleoplasm
Gene Ontology:
Molecular function: protein binding; protein-containing complex binding; ubiquitin protein ligase binding
Biological process: DNA damage response; positive regulation of double-strand break repair; positive regulation of maintenance of mitotic sister chromatid cohesion; positive regulation of protein-containing complex assembly; protein localization to site of double-strand break; chromatin looping; double-strand break repair via homologous recombination; protein sumoylation; regulation of telomere maintenance
Cellular component: nucleus; site of double-strand break; centrosome; chromosome, telomeric region; cytoplasm; nuclear inclusion body; nucleosome; Smc5-Smc6 complex; chromosome
Genetic constraint (gnomAD): Loss-of-function variants: 79 observed, 93.48 expected, observed/expected ratio (o/e) 0.85, 90% interval 0.7 to 1.02. The upper end of that interval is the gene's LOEUF score, 1.02, which puts it in group 4 of 6, group 1 being the genes least tolerant of losing a copy. Missense variants: 992 observed, 1,030.6 expected, observed/expected ratio (o/e) 0.96, 90% interval 0.91 to 1.01. Synonymous variants: 369 observed, 353.27 expected, observed/expected ratio (o/e) 1.04, 90% interval 0.96 to 1.14.
Homologues: Orthologues: chimpanzee SLF1 (99% identical), macaque SLF1 (98% identical), pig SLF1 (89% identical), rabbit SLF1 (86% identical), dog SLF1 (85% identical), guinea pig SLF1 (81% identical), rat Slf1 (80% identical), mouse Slf1 (80% identical), tropical clawed frog slf1 (39% identical), zebrafish slf1 (24% identical). Paralogues in human: TOPBP1 (13% identical).
Diseases named in the same sentence as SLF1 in open-access papers:
SLF1 is named in the same sentence as 8 diseases in open-access papers, as found by Europe PMC text mining. Sharing a sentence is not in itself a finding about the gene and the disease. The quoted sentences say what the papers report.
Atrophy (1 paper, 2022). Any weakening or degeneration, especially through lack of use. "This indicates that the degree to which EE positively mitigates GM and WM atrophy of the ageing brain is dependent in part, on the degree to which EE has altered neurite dispersion properties of the right SLF1." (PMID 35474852, 2022).
Ventriculomegaly (1 paper, 2023). An increase in size of the ventricular system of the brain. "Both individuals with the WNT8B and SLF1 variants displayed the classical triad of AIC with accompanying features including ventriculomegaly, atrophy of the cerebellar hemispheres, scoliosis and skeletal abnormalities." (PMID 37628618, 2023).
SLF1 also shares sentences with these, for which no sentence is quoted: cancer (2 papers); anemia (1); Atelís Syndrome (1); microcephaly (1); neurodegenerative disease (1); neurodevelopmental disorder (1).